PIN1 (peptidylprolyl cis/trans isomerase, NIMA-interacting 1)
Diseases named in the same sentence as PIN1 in open-access papers (continued):
Sharing a sentence is not in itself a finding about the gene and the disease.
glioma (13 papers, 2013 to 2025). A benign or malignant brain and spinal cord tumor that arises from glial cells (astrocytes, oligodendrocytes, ependymal cells). "High Pin1 expression is associated with SUMO1-modified protein hypersumoylation in glioma stem cells (GSCs), but the underlying mechanisms remain elusive." (PMID 38167292, 2024). "In conclusion, we have shown that Pin1 and Nanog expression in human gliomas appears to be associated with the pathogenesis of gliomas." (PMID 23708493, 2013). "In the present study, the association between Pin1 and Nanog in human gliomas, the subcellular localization and coexpression of Pin1 and Nanog in glioma cells were investigated." (PMID 23708493, 2013). "An association between higher Pin1 expression and aggressive grades of gliomas was also demonstrated, which suggests that Pin1 may participate in the pathogenesis of gliomas, which are defined as poorly differentiated according to purely histopathological criteria." (PMID 23708493, 2013). "Previously, we determined that Pin1, whose expression also increases in correlation with the tumor grade of gliomas, contributed to tumorigenic properties of gliomas by playing an active role in cell growth, migration, and angiogenic potential." (PMID 36766769, 2023). "Recently, juglone, a Pin1 inhibitor, was shown to exhibit potent anticancer activity in various tumor cells including U251 glioma cells, and it was observed to disrupt angiogenesis." (PMID 30959841, 2019). "Although the mechanisms responsible for PIN1 upregulation in gliomas remain to be fully defined, several studies provide evidence for multiple PIN1 functions in glioblastoma." (PMID 30314361, 2018). "This possibility is consistent with the results of later studies in which endogenous PIN1 activity was inhibited in glioma cells using the potent PIN1 pharmacological inhibitor, juglone." (PMID 30314361, 2018). "As expected, a similar differential expression pattern was observed; the higher expression of Pin1 correlated with a more highly malignant glioma (F=22.962, P<0.01)." (PMID 23708493, 2013). "We have shown that high Pin1 and Nanog expressions were detected in glioma specimens by RT-PCR, western blotting and immunohistochemical analysis." (PMID 23708493, 2013). "In the present study, we first investigated the expressions of Pin1 and Nanog in gliomas, as well as the correlation between them." (PMID 23708493, 2013). "The results indicated that the expression levels of Pin1 and Nanog were positively correlated in gliomas (r=0.209, P<0.05), which suggest a high correlation between the levels of Pin1 and Nanog in glioma development." (PMID 23708493, 2013). "Densitometric evaluation of the relative expression showed that the mRNA level of Pin1 in the high-grade primary gliomas was significantly higher than that in the low-grade gliomas (F=21.814, P<0.01)." (PMID 23708493, 2013). "For both Pin1 and Nanog, their mRNA and protein expressions were detected and found highly expressed in human gliomas and positively correlated with pathological grade of patients with gliomas." (PMID 23708493, 2013). "We also confirmed that the co-location of Pin1 and Nanog was mainly in the perinuclear space in the cytoplasm of glioma cells." (PMID 23708493, 2013). "Co-localization of Pin1 and Nanog was observed in the perinuclear space in the cytoplasm of glioma cells detected by immunofluorescence staining." (PMID 23708493, 2013). "Significantly higher mRNA and protein expression levels of Pin1 and Nanog were demonstrated in 120 glioma specimens of different pathological grades by RT-PCR, immunohistochemistry staining and western blot analysis." (PMID 23708493, 2013). "In our research, we found significantly higher Pin1 mRNA and protein expression in glioma samples as compared with the normal brain tissue samples." (PMID 23708493, 2013). "Moreover, Pin1 expression in gliomas is known to increase in correlation with tumor grade, similar to EGFR expression." (PMID 36766769, 2023).
glioma (continued). "We showed that CDK5 regulates glioma tumorigenicity by promoting TRIM59 nuclear translocation via PIN1/importin α5 axis, leading to STAT3 signaling activation, and demonstrate that CDK5 mediates EGFR-stimulated STAT3 signaling through activation of the TRIM59/mH2A1 axis in GBM." (PMID 31488827, 2019). "Furthermore, Pin1 expression is positively correlated and co-located with Nanog expression in glioma." (PMID 23708493, 2013). "We further confirmed that majority of glioma cells coexpressed Pin1 and Nanog, which were co-located in the perinuclear space in the cytoplasm of glioma cells, where they may interact and have a cytoplasmic function to affect glioma cells." (PMID 23708493, 2013). "The present study investigated the expression and relationship of Pin1 and Nanog in human gliomas." (PMID 23708493, 2013). "Targeting the Pin1-Nanog pathway may be an approach to improve the therapeutic intervention for poorly differentiated gliomas." (PMID 23708493, 2013). "Positive immunostaining of Pin1 and Nanog was observed in glioma cells." (PMID 23708493, 2013). "However, further study is required to determine the precise role of the Pin1-Nanog pathway, and the mechanism of Pin1-Nanog transcriptional regulation in gliomas." (PMID 23708493, 2013). "We initially analyzed the expression profiles of 120 gliomas to examine whether Pin1 was enriched in glioma tissues." (PMID 23708493, 2013). "Significantly positive correlation between Pin1 and Nanog in gliomas indicated that Pin1 and Nanog may be related to tumorigenesis and development of glioma cells." (PMID 23708493, 2013). "In addition, Pin1 expression was mainly confined to the nuclei in low grade glioma in a lower degree of enrichment and weak expression, but exhibited enhanced expression in both the cytoplasm and nuclei of high grade glioma." (PMID 23708493, 2013). "Pin1 was expressed in both the cytoplasm and nuclei of U87 glioma cells." (PMID 23708493, 2013). "On the basis of these findings, we hypothesize that the Pin1-Nanog pathway may be important in the tumorigenesis of the gliomas." (PMID 23708493, 2013). "Therefore, Pin1 inhibitors should be investigated as a new chemotherapeutic drug that may enhance the clinical management of human gliomas." (PMID 30959841, 2019). "The involvement of PIN1 in multiple oncogenic processes in glioblastoma suggests that PIN1-mediated cis-trans isomerization mechanisms contribute to gliomagenesis and that strategies aimed at impairing PIN1 activity might be attractive anti-glioma therapies." (PMID 30314361, 2018). "Moreover, a positive correlation of Pin1 and Nanog expression in human gliomas was noted." (PMID 23708493, 2013). "Further research is required to elucidate the difference in response and control of expression of Pin1 and Nanog in glioma, and to explore if Pin1 could act as a ubiquitination switch in regulating glioma cellular functions through Nanog conformational changes." (PMID 23708493, 2013). "Pin1 and Nanog may play an important role in glioma tumorigenesis through interaction." (PMID 23708493, 2013). "Furthermore, we frequently observed a positive relationship between Pin1 and Nanog in gliomas." (PMID 23708493, 2013). "For example, in glioma stem cells, it was found that ubiquitin specific peptidase 34 (USP34) regulated glioma stem cell progression by directly heterodimerizing UBE2I and regulating the aberrant expression of Pin1 at the post-translational level." (PMID 40025314, 2025). "Together, these results suggest the combination of PIN1 and HDAC inhibitors as a promising therapeutic strategy for H3-K27M gliomas." (PMID 39093942, 2024). "Consistently, PIN1 attenuation leads to decreased levels of vascular endothelial growth factor (VEGF) and matrix metalloproteinase 9 in glioma cells." (PMID 30314361, 2018). "Western blot analysis confirmed that Pin1 was highly expressed in both U87 cells and WHO IV glioma tissues (t=1.138, P>0.05)." (PMID 23708493, 2013).
glioma (continued). "RT-PCR analysis of cells revealed the expected 427-bp Pin1 band in both the U87 cells and WHO IV glioma tissues (t=0.259, P>0.05)." (PMID 23708493, 2013). "Additionally, Pin1 and Nanog expression were positively correlated in glioma tissues, indicating they may interact to affect cell proliferation and maintain the cell viability and stemness of glioma." (PMID 23708493, 2013). "Furthermore, Pin1 and Nanog were co-located in the perinuclear space in the cytoplasm of glioma cells, where they may interact and have a cytoplasmic function to affect glioma cells." (PMID 23708493, 2013). "The genes downregulated by Sulfopin were also enriched for MYC-bound genes identified in several non-glioma cell lines, supporting a role for PIN1 in activation of the MYC pathway also in these glioma cells." (PMID 39093942, 2024). "Additionally, Pin1 facilitates the sumoylation of PML by SUMO1 in glioma stem cells, which enables PML to interact with and stabilize c-Myc, thereby permitting the survival and carcinogenic potential of glioma stem cells." (PMID 38727267, 2024). "PIN1 is overexpressed in human gliomas compared to non-cancerous brain cells." (PMID 30314361, 2018).
cervical cancer (12 papers, 2017 to 2025). A primary or metastatic malignant neoplasm involving the cervix. "The expression of Pin1 was positively associated with lymph node metastasis and c-Jun expression in human cervical cancer tissues." (PMID 32010480, 2020). "A research reported that PIN1 promoted the proliferation and invasion of cervical cancer cells by inhibiting ferroptosis, which was mediated by the inhibition of the cGAS-STING pathway." (PMID 41142804, 2025). "Subsequent investigation suggested that USP34 enhanced the expression of PIN1 via SUMOylation in cervical cancer cells, thereby achieving the tumor-promoting effects." (PMID 41142804, 2025). "More importantly, we found that matrix stiffness regulates YAP nuclear translocation via Pin1 in a non‐Hippo pathway thus promote EMT in cervical cancer." (PMID 36684109, 2023). "We verified the effect of matrix stiffness on EMT in cervical cancer and the role of yes‐associated protein (YAP) and PPIase non‐mitotic a‐interaction 1 (Pin1) in it." (PMID 36684109, 2023). "In summary, the present study demonstrated from in vivo and in vitro experiments that matrix stiffness promotes EMT in cervical cancer, and the Pin1/YAP pathway plays an important role in this." (PMID 36684109, 2023). "More importantly, we found that matrix stiffness regulates YAP nuclear translocation via Pin1 in a non‐Hippo pathway thus promoting EMT in cervical cancer." (PMID 36684109, 2023). "Pin1 also contributes to cisplatin resistance through upregulation of the FoxM1 and Wnt/β-catenin signaling pathway in cervical cancer cells." (PMID 33807199, 2021). "To explore the role of Pin1 and c-Jun in cervical cancer progression, we assessed the expression of Pin1 and c-Jun in normal cervical tissues and cancerous cervical tissues by western bloting." (PMID 32010480, 2020). "The results of our investigation revealed that the downregulation of Pin1 by shRNA or KPT-6566 inhibited the growth of human cervical cancer cells (CCCs)." (PMID 32010480, 2020). "The results showed that Pin1 and c-Jun expression was significantly higher in cervical cancer tissue than that in normal cervical tissue." (PMID 32010480, 2020). "Pin1 increases the survival of cisplatin-treated cervical cancer cells through Wnt/β-catenin and FoxM1 signaling." (PMID 32258027, 2020). "We previously showed that Pin1 expression is a key event in clinical cervical cancer tissue cases, but the therapeutic potential of Pin1 in treating CC is still unclear." (PMID 32010480, 2020). "To investigate the roles of Pin1 and c-Jun in cervical cancer, we first examined the expression of Pin1/c-Jun in LSILs, HSILs and SCC patient tissues." (PMID 32010480, 2020). "Research indicates that HPV-infected cervical lesions exhibit an elevated level of Pin1215, but the relationship of HPV-induced Pin1 and genome instability in cervical cancer requires a deeper investigation." (PMID 30158600, 2018). "Pin1 also enhances the survival of cisplatin-treated cervical cancer cells by upregulating Wnt/β-catenin and FoxM1 pathways." (PMID 30158600, 2018). "In addition, knockdown of PIN1 significantly downregulated the survival rate of cervical cancer cells." (PMID 41142804, 2025). "Inhibition of Pin1 has been reported to significantly reduce the proliferation and metastasis of cervical cancer cells, and it may serve as a new therapeutic target for cervical cancer." (PMID 36684109, 2023). "To determine the role of Pin1 in the regulation of EMT in cervical cancer by matrix stiffness, we upregulated Pin1 expression in hela cells using an expression plasmid and inhibited Pin1 expression in hela cells using the Pin1 inhibitor Juglone38, 39 and verified its effect using western blotting." (PMID 36684109, 2023). "This study provides evidence that targeting ECM stiffness can hinder EMT in cervical cancer and indicates that Pin1 and YAP may be a promising target for treatment against cervical cancer." (PMID 36684109, 2023).
cervical cancer (continued). "Immunohistochemical staining showed that E‐cadherin expression was more in the Juglone‐treated tumor than in the DMSO treated tumor, and Vimentin expression was less than in the DMSO‐treated tumor, indicating that downregulation of Pin1 expression inhibits EMT in cervical cancer in vitro." (PMID 36684109, 2023). "Moreover, it has been reported that lncRNA FBXL19-AS1 regulates invasion, migration, and growth of cervical cancer by miR-193a-5p/PIN1 axis." (PMID 35847361, 2022). "Furthermore, the protein levels of Pin1 and c-Jun were significantly increased in high grade cervical cancer (TNM III, TNM IV), demonstrating that increased levels of Pin1 and c-Jun were associated with the TNM stage of human cervical cancer." (PMID 32010480, 2020). "We inferred that other published miR-140 targets, such as ADAMTS5 and IGFBP5 in colorectal cancer, Pin1 in liver cancer, and IGF2BP1 in cervical cancer, which are associated with tumor migration and invasion, may contribute to these GC cell phenotypes." (PMID 28818100, 2017). "Pin1 has also been reported to enhance EMT and chemoresistance by upregulating FoxM1 and the Wnt/β-catenin signaling pathway in cervical cancer cells." (PMID 33807199, 2021). "Our results suggest suggested that Pin1 could be a potent therapeutic target in cervical cancer treatment, and we believe that KPT-6566 has good prospects for the treatment of cervical cancer in combination with anti-tumour drugs." (PMID 32010480, 2020).
leukemia (12 papers, 2016 to 2024). A malignant (clonal) hematologic disorder, involving hematopoietic stem cells and characterized by the presence of primitive or atypical myeloid or lymphoid cells in the bone marrow and the blood. "For example, Pin1 associates with the pThr254-Pro motif of transcription factor NF-κB p65 subunit, leading to the increased protein stability of p65 and enhanced transcriptional activity of NF-κB in various cancers, including leukemia, lymphomas, and glioblastoma." (PMID 32296699, 2020). "Alternatively, we diminished endogenous Pin1 level by employing a well-known therapeutic drug for leukemia, all-trans retinoic acid (ATRA), which directly binds to and promotes degradation of Pin1." (PMID 39609819, 2024). "C/EBPα-p30, a mutant of transcription factor C/EBPα, which was found in around 9% of acute myeloid leukemia (AML) patients, induces Pin1 expression by recruiting E2F1 in the PIN1 promoter and enhances leukemia." (PMID 32296699, 2020). "ATRA inhibits leukemia, breast, and liver cancer by targeting isomerase Pin1, a master regulator of oncogenic signaling networks." (PMID 30093655, 2018). "This implies that Pin1 can maintain the leukemia stem cell population and therefore represent an ideal target for the effective treatment of AML." (PMID 29848341, 2018). "We also examined Pin1 expression in human leukemia cell lines, including six AML cell lines (Kasumi-1, U937, K562, NB4, HL-60, and KG-1a) and two ALL cell lines (Nalm-6 and Molt-4)." (PMID 29848341, 2018). "b The stronger signals of Pin1 protein levels of healthy controls and leukemia cell lines were detected with a 5 min exposure of blot than with a 30 s exposure of blot." (PMID 29848341, 2018). "First, we found that the expression of Pin1 mRNA and protein was significantly increased in both de novo leukemia clinical samples and multiple leukemia cell lines, compared with healthy controls." (PMID 29848341, 2018). "The mRNA and protein levels of Pin1 were detected in samples from de novo leukemia patients and healthy controls using real-time quantitative RT-PCR (qRT-PCR) and western blot." (PMID 29848341, 2018). "To investigate the potential clinical significance of Pin1 in leukemia, we examined the relative expression of PIN1 mRNA in bone marrow mononuclear cells from 107 newly diagnosed leukemia patients and 43 healthy bone marrow donors." (PMID 29848341, 2018). "Both PIN1 mRNA and Pin1 protein levels were found to be significantly higher in human leukemia cell lines as compared with bone marrow cells of healthy control." (PMID 29848341, 2018). "Herein we provided the novel evidence showing that ATRA, a potent Pin1 inhibitor well known for its therapeutic effect on leukemia and other cancer, effectively increases endogenous CaV2.1 protein level in neurons, as well as notably reducing ER-associated degradation of EA2-causing CaV2.1 mutants." (PMID 39609819, 2024). "Since ATRA induces differentiation in various leukemia cell lines, it is unclear whether differentiation would affect Pin1 levels." (PMID 29848341, 2018). "Moreover, Pin1 deletion prevents leukemia progression by reducing Notch3 expression and blocking the expansion/invasiveness of circulating CD4+CD8+ T-cells in N3-ICtg blood." (PMID 30038265, 2018). "A positive correlation of PIN1 mRNA and Pin1 protein levels was also found in leukemia cell lines." (PMID 29848341, 2018). "Silencing Pin1 can delay the progression of lymphoma disease in Eμ-myc transgenic mice; however, much less is known about the role of Pin1 in the development and treatment of other more common and heterogeneous leukemia." (PMID 29848341, 2018). "Furthermore, genetic or chemical inhibition of Pin1 in human multiple leukemia cell lines potently inhibited multiple Pin1 substrate oncoproteins and effectively suppressed leukemia cell proliferation and colony formation ability in cell culture models in vitro." (PMID 29848341, 2018).
leukemia (continued). "Given the overexpression of Pin1 in AML, including biopsied bone morrow leukemia cells and established human AML cell lines, the question remains as to whether Pin1 plays any role in leukemogenesis." (PMID 29848341, 2018). "Moreover, tetracycline-inducible Pin1 knockdown and slow-releasing ATRA potently inhibited tumorigenicity of U937 and HL-60 leukemia cells in xenograft mouse models." (PMID 29848341, 2018). "In our studies, Pin1 degradation is not related to the effect of leukemia cell differentiation." (PMID 29848341, 2018). "Thus, there is an urgent need to develop a longer half-life ATRA formulation or Pin1-targeted ATRA derivatives or more specific Pin1 inhibitors for treating non-APL leukemia and other cancers." (PMID 29848341, 2018). "Notably, the cooperative ability of ATO and ATRA to eliminate TICs in TNBC by targeting Pin1 is consistent with the previous findings that genetic or chemical inhibition of Pin1 induces PML/RARα degradation to eradicate leukemia stem cells and treat APL without inducing myeloid differentiation." (PMID 30093655, 2018).